LEP (leptin)
Diseases named in the same sentence as LEP in open-access papers (continued):
Sharing a sentence is not in itself a finding about the gene and the disease.
diabetes (continued). "Also, leptin and HOMA-IR levels increased, while insulin and HOMA-β levels decreased in the diabetes control group." (PMID 33641315, 2021). "Leptin, adiponectin, GDF-15 and FGF-21 changes were related to weight loss not remission of diabetes." (PMID 33925808, 2021). "One can expect there is no such correlation, as uterine fibroids’ pathogenesis (contrary to diabetes mellitus and glucose intolerance) reaches to quite different origins than metabolism of carbohydrates and leptin should not play any role here." (PMID 34399708, 2021). "The lack of degenerative changes in IVDs of Db/Db mice is in contrast with our previous studies on western style diets in C57BL/6J mice, which demonstrated that pre-diabetes contributed to inferior vertebral quality, accelerated progression of IVD degeneration, and increased leptin levels." (PMID 32374776, 2020). "Obese participants were more likely to have a significantly higher BMI, FPG, leptin, and hsCRP levels irrespective of diabetes status than non-obese participants." (PMID 32277104, 2020). "Serum leptin levels were significantly higher in COPD patients with concomitant type 2 diabetes mellitus, regardless of genotype." (PMID 33072207, 2020). "The blood glucose levels in the different diabetes models did not reflect the endogenous leptin levels (gray columns)." (PMID 31743040, 2020). "Consistent with the increased leptin mRNA expression in the mesenteric fat of HFD-treated mice, leptin mRNA expression in mesenteric fat is positively correlated with the BMI values of patients without diabetes." (PMID 32733043, 2020). "The copy number of mtDNA in various fat stores was higher in obese patients with type 2 diabetes than in obese patients without diabetes or in the control subjects and was related to the levels of leptin and proinflammatory cytokines." (PMID 30871567, 2019). "The suggestion that the effect of the antioxidants NAc and apocynin is leptin independent is further supported by our observation that they mediate an effect during the early phase of diabetes development in iFIRKO mice in which leptin is almost absent." (PMID 31309261, 2019). "The expression of Slc39a5 was significantly reduced in all three obese and diabetes murine models, which suggests that the leptin signaling does not directly regulate Slc39a5 expression." (PMID 30324491, 2019). "Leptin levels can be regulated by body mass index (BMI) and body fat mass; therefore, obese and malnourished people as well as patients with diabetes mellitus were not included so as to minimize the interference of possible confounding factors." (PMID 31595672, 2019). "Hemoglobin A1c did not strengthen the prediction algorithm of diabetes, determined by our proposed biomarkers, leptin, adiponectin, and insulin." (PMID 31379415, 2019). "Obese persons without diabetes were about three times more likely to have higher leptin levels compared with their obese diabetic counterparts (Odds ratio = 3.315, p < 0.001)." (PMID 29422086, 2018). "Diabetic mice suffering from leptin-resistance on the db/db background were employed as a rodent model for diabetes mellitus type 2 and C57BL/6 wild-type animals without impairment of leptin signaling served as controls." (PMID 29593651, 2018). "In another study, while then baseline concentrations of leptin were not different, after three months, pioglitazone decreased the leptin concentrations in men with type 2 diabetes mellitus." (PMID 29791472, 2018). "In our study, the racial differences in the distribution of leptin and resistin mirror racial differences in the prevalence of diabetes but not BMI." (PMID 29662629, 2018). "When the study participants were classified based on diabetes, plasma level of Leptin was significantly higher in obese non-diabetic individuals (10.11 ± 0.95 ng/mL) than in non-obese non-diabetic individuals (5.31 ± 0.44 ng/mL) with P < 0.0001." (PMID 30131766, 2018).
diabetes (continued). "Increases in inflammatory cytokines in diabetes promote tumour development, which include interleukin-6 (IL-6), monocyte chemoattractant protein, plasminogen activator inhibitor-1 (PAI-1), adiponectin, leptin, and tumor necrosis factor-alpha." (PMID 30271790, 2018). "For example, three or four months of pioglitazone treatment are not able to change leptin levels in patients with type 2 diabetes mellitus." (PMID 29791472, 2018). "Obese persons with diabetes were about three times more likely to have lower leptin levels than their obese non-diabetic counterparts (Odds ratio = 3.315, CI = 1.918, 5.824; p < 0.001)." (PMID 29422086, 2018). "For example, it was revealed that plasma leptin level is not influenced by the presence of type 2 diabetes mellitus, or short-term treatment with diet and/or sulphonylurea or metformin, but it has direct relation to glycaemic control." (PMID 30486321, 2018). "The conducted studies did not indicate a relationship between the leptin concentration and the value of the glycated haemoglobin percentage in the blood of the individuals suffering from diabetes both before and after insulin therapy." (PMID 28758947, 2017). "The conducted studies did not indicate the relationship between the concentration of leptin and adiponectin in the examined sick individuals, both those with newly-diagnosed diabetes and those after implementation of insulin therapy." (PMID 28758947, 2017). "Chronic ICV leptin infusion for 7 days did not alter MAP in either group but completely reversed the bradycardia caused by diabetes in control rats." (PMID 29190687, 2017). "The parameters of the secretory function of the adipose tissue showed an increase, although not statistically significant, of leptin levels and a statistically significant decrease (p < 0.05) of adiponectin values in diabetics compared to the control group." (PMID 28468307, 2017). "We found that hypophysectomy attenuated leptin’s effects to raise HR but failed to alter leptin’s chronic CNS-mediated actions to suppress food intake or to reduce blood glucose in STZ-induced diabetes in rats." (PMID 29190687, 2017). "Pathway analysis of our proteome profile indicated that diabetes is associated with activation of inflammatory and oxidative response proteins such as TNF–α, NFκB, leptin, leptin receptors, and p38 MAPK, factors that have been shown to contribute to micro and macrovascular complications of diabetes." (PMID 29121074, 2017). "Moreover, all the metabolic indicators including TC, TG, FFA, GLU, insulin, HOMAIR, HOMAIS, leptin, HbA1C, HDL, LDL, and TNF were previously proved to have the relationship with chronic disease of hypertension, diabetes mellitus, and cardiovascular disease." (PMID 28115972, 2017). "During the development of the type 2 diabetes mellitus rat model, the changes in hypothalamic NPY contents and its correlation with the insulin, leptin, and ghrelin levels, as well as the potential mechanism underlying their interactions have not yet been reported." (PMID 27867820, 2016). "Therefore, high adiponectin and/or low leptin levels can enhance insulin sensitivity in WAT and increase FAO in the liver, thus leading to the improvement of diabetes." (PMID 27589792, 2016). "Over a 3-month study period, a Palaeolithic diet resulted in reduced fasting plasma leptin levels, but did not change fasting levels of insulin, C-peptide, glucagon, incretins, ghrelin and adipokines compared to the currently recommended diabetes diet." (PMID 27216013, 2016). "By contrast, we were encouraged by the results of leptin treatment which clearly prevented onset of diabetes in Akita mice without inducing fatal hypoglycemia." (PMID 28702245, 2016). "Therefore, the objective of this study was to investigate the relationship between the serum levels of leptin, TNF-α, and SAA in diabetes mellitus type 2 with nutritional status of vitamins E and C." (PMID 26693410, 2015).
diabetes (continued). "To understand the mechanism underlying the effects of ASCs on CAIA, we examined the serum levels of five cytokines (IL-15, IL-1α, IL-6, IL-7, and TNFα), five diabetes-related hormones (resistin, GIP, GLP-1, ghrelin, and leptin), and adiponectin using multiplex immunoassays." (PMID 26210906, 2015). "Plasma leptin levels are positively correlated with female sex, BMI, and age but not with diabetes duration, HbA1c, or total insulin dose per kilogram." (PMID 26273677, 2015). "In our analysis, adiponectin concentration appeared to partially mediate the effect of smoking on diabetes, while leptin and CRP levels did not." (PMID 25400076, 2015). "The two-way ANOVAs confirmed these main effects and also found a significant interaction between gender and diabetes for the serum, but not CSF leptin." (PMID 25835291, 2015). "During the 4 week intervention period following the onset of diabetes, the insulin-treated mice maintained on a HFD continued to gain weight, more body fat, and even higher fasting insulin, C-Peptide, and leptin levels (2C & D) whereas sham-treated diabetic mice showed a tendency to lose weight." (PMID 25633992, 2015). "In contrast, earlier investigations comparing Sudanese adults with and without diabetes have reported elevated plasma leptin levels in subjects with diabetes." (PMID 25993052, 2015). "Longitudinal follow-up examinations of this cohort will clarify the role of leptin in autonomic dysfunction in patients with and without diabetes." (PMID 26338087, 2015). "Firstly, leptin therapy itself is unlikely to be effective in improving diabetes in humans because of the known leptin-resistant characteristic of these subjects." (PMID 25870537, 2015). "In contrast, neither the indirect effects of smoking on diabetes through leptin nor CRP levels were significant, as the corresponding BC 95% CIs included zero." (PMID 25400076, 2015). "Recently, leptin has been shown to suppress glucagon and correct diabetes in mice, in the absence of insulin." (PMID 23132340, 2013). "Dietary treatment with high-fat diets (HFD) triggers diabetes and hyperleptinemia, concomitantly with a partial state of leptin resistance that affects hepatic and adipose tissue but not the heart." (PMID 24298268, 2013). "This study aimed to evaluate variations in serum leptin levels in non-obese subjects with type 2 diabetes mellitus (T2DM)." (PMID 23853613, 2013). "In summary, in a multiethnic sample of US adults, we found that higher plasma leptin levels are associated with CKD, independent of traditional factors such as age, sex, smoking, alcohol intake, BMI, diabetes, hypertension and serum cholesterol." (PMID 22666590, 2012). "The observed impaired glucose tolerance in HFD-treated mice was accompanied by a hyperinsulinaemic state and markedly raised levels of circulating leptin, which both represent well-described features of a developing HFD-induced type 2 Diabetes mellitus in mice." (PMID 21318183, 2010). "Patients with a preexisting diabetes (n = 46) had significantly higher serum leptin levels (median 8.8 ng/mL) than patients without diabetes (n = 91, median leptin 4.9 ng/mL, P = .013)." (PMID 20871818, 2010). "Serum leptin was significantly higher in the men with diabetes than in their non-diabetic counterparts (12.4 [3.2–72]; p = 0.0001)." (PMID 17617917, 2007). "Other proteins tested in similar experiments involved detection of tubulin from human plasma and insulin and leptin from diabetes serum samples (data not shown)." (PMID 16281978, 2005). "Collectively, this panoramic view articulates a core mitochondrial dysfunction signature common to sarcopenia and diabetes, a classical adipokine–mitochondria support network, a novel counter-regulatory myokine/adipokine module, and tissue- and disease-specific modifiers (NNMT, LEP, and AdipoQ)." (PMID 40869253, 2025).
diabetes (continued). "Notably, the impact of diabetes varied by sex; it was not significant in men, while women with diabetes had lower plasma leptin levels compared to those without diabetes." (PMID 40943431, 2025). "Various hormone-like molecules (adiponectin, leptin, resistin, apelin, visfatin, adipsin, omentin, chemerin, and metrnl) are classified as adipokines that are produced by WAT and play a multifaceted role in numerous diseases, including diabetes, atherosclerosis, CVD, and immune disorders." (PMID 39538244, 2024). "Leptin levels were found to be higher in endometrial cancer patients compared to the control group, but this was not significant when adjusted for BMI, parity, and diabetes." (PMID 38339282, 2024). "Additionally, patients with CP with diabetes mellitus (DM) were found to have higher levels of leptin than patients with CP without DM." (PMID 38397476, 2024). "Several factors can influence this relationship, including the presence or absence of diabetes (e.g., T2D), the duration of hyperglycemia, the levels of leptin or adiponectin from the adipose tissue, and the impact of high insulin levels on sex hormone-binding globulin (SHBG)." (PMID 38731059, 2024). "In addition, low-AGE diets have been connected to reductions in inflammatory markers, 8-isoprostane, leptin, circulating AGE levels, RAGE, as well as to increased adiponectin levels and mononuclear cells sirtuin-1 in healthy subjects and patients with diabetes." (PMID 39518960, 2024). "The potential role of adipokines, including adiponectin and leptin, in the development of diabetic complications like DPN is gaining recognition due to their involvement in metabolic regulation and inflammatory processes, key factors in diabetes and its sequelae." (PMID 39735639, 2024). "On the other hand, leptin level was elevated in obese subjects whether they have diabetes or not and it was correlated with BFM." (PMID 36950695, 2023). "Leptin expression is also known to be influenced by the presence of ovarian sex steroids levels of which are expected to be higher in the younger premenopausal groups without diabetes." (PMID 35933445, 2022). "As expected, APF could not ameliorate diabetes and metabolic syndromes without leptin presence in ob/ob mice." (PMID 36046814, 2022). "Finally, we used multivariate linear regression to evaluate the relationship between serum leptin and eGFR levels with adjustment for age, sex, smoking status, drinking status, body mass index (BMI), uric acid levels, hypertension (HTN), diabetes mellitus (DM), and dyslipidemia." (PMID 36619557, 2022). "The current understanding of metabolic syndrome (MS) and diabetes mellitus type 2 (DM2) is that formation of their main components is influenced by the substrate-energy role played by lipocyte products and informational signalling molecules, such as leptin and adiponectin." (PMID 36117520, 2022). "Many cardiometabolic diseases or dysfunctions, such as metabolic syndromes, type 2 diabetes mellitus (DM), or hypertension (HTN), are positively related to serum leptin levels." (PMID 36698957, 2022). "Considering that postprandial levels of oxyntomodulin were found to be markedly lower in NODAP compared with T2DM and healthy controls (independent of insulin secretion), it is possible that leptin is an important factor in differentiating the pathogenesis of the two diabetes states." (PMID 34684558, 2021). "In an RCT that included 40 patients that compared the glycemic control effects of gastric cancer surgery according to surgery type, patients who experienced improvement or remission of diabetes at 12 months after surgery had higher preoperative leptin levels than those who did not." (PMID 34501456, 2021). "Besides the implication of the insulin/IGF-1 axis, diabetes involve the dysregulation of other hormones, which implicate HIF1 signaling and may promote breast carcinogenesis such as the adiponectin-leptin duo." (PMID 34225729, 2021).
diabetes (continued). "However, earlier animal models of type 1 diabetes are severely catabolic with very low endogenous leptin levels, unlike most patients with diabetes." (PMID 31743040, 2020). "However, it is not yet clear how plasma leptin regulate autonomic function in patients with diabetes and prediabetes." (PMID 33076921, 2020). "A recent study from Japan shows that plasma leptin level is comparable between diabetic and non-diabetic patients, despite the fact that BMI, visceral fat area, and subcutaneous fat area are significantly higher in patients with diabetes." (PMID 33076921, 2020). "Similarly, patients with prediabetes and T2DM have significantly higher circulating leptin levels than patients without diabetes." (PMID 32733043, 2020). "Leptin also has a glucose-lowering effect by a mechanism independent of insulin in uncontrolled diabetes, and it normalizes the hepatic glucose production by increasing glucose uptake rate in peripheral tissues such as heart, brown adipose tissue and skeletal muscles." (PMID 31231496, 2019). "Therefore, the higher serum concentrations of adiponectin and leptin in the 1X and 5X groups in the present study indicate that TGPE may improve STZ/HFD-induced diabetes by stimulating the secretion of adiponectin and leptin in rats." (PMID 29670038, 2018). "In addition, adiponectin and leptin serum concentrations may reflect adipose tissue dysfunction in IGR and might promote early pathogenetic development toward diabetes." (PMID 28893239, 2017). "This small trial showed that a Palaeolithic diet decreased fasting plasma leptin, but did not affect fasting levels of insulin, C-peptide, glucagon, incretins, ghrelin and adipokines significantly compared to the currently recommended diabetes diet." (PMID 27216013, 2016). "During the development of the type 2 diabetes mellitus rat model, the hypothalamic NPY content and NPY mRNA expression increased in a time-dependent manner, which was positively correlated with the changes of the serum insulin and leptin and negatively correlated with the plasma ghrelin." (PMID 27867820, 2016). "In addition, apolipoprotein A1 increased (with the exception of patients with diabetes receiving placebo-etanercept) and adiponectin increased slightly through week 24; leptin and apolipoprotein B did not change." (PMID 27704313, 2016). "Study FHA101 (ClinicalTrials.gov identifier: NCT00677313) was an open-label, expanded-access, long-term clinical effectiveness and safety study in 23 patients with partial lipodystrophy and diabetes and/or hypertriglyceridemia with no prespecified leptin level." (PMID 27642538, 2016). "The metabolic disorder type 2 diabetes mellitus is similarly related to irregular levels of lipids and lipoproteins, including cholesterol, low-density lipoprotein (LDL), very low-density lipoprotein (VLDL), high-density lipoprotein (HDL), triglyceride (TG), as well as leptin and adiponectin." (PMID 26699937, 2015). "Plasma leptin level in diabetes is rather controversial; one recent study does not observe any significant difference between diabetic and non-diabetic subjects, others reported significant lower level in type 1 diabetic subjects and type 2 diabetics with similar adiposity." (PMID 26338087, 2015). "In this large population-based sample of Asian adults, higher serum leptin, adiponectin levels and LAR were positively associated with CKD, independent of age, gender, education level, BP, diabetes mellitus, CVD, smoking, alcohol intake, and total and HDL cholesterol levels." (PMID 25793395, 2015). "They raised the plasma leptin but did not reverse the diabetes-induced hypoadiponectinemia." (PMID 24995315, 2014). "Furthermore, correlation of fetal leptin levels with fetal EPO levels in T1D parallels the finding that leptin is regulated by hypoxia through transcriptional induction by HIF1 and can thus represent another manifestation of fetal hypoxia in diabetes mellitus." (PMID 25258707, 2014).